ABCG2 (ATP binding cassette subfamily G member 2 (JR blood group))
Diseases named in the same sentence as ABCG2 in open-access papers (continued):
Sharing a sentence is not in itself a finding about the gene and the disease.
Hypertension (15 papers, 2014 to 2025). The presence of chronic increased pressure in the systemic arterial system. "Our study also established that HUA risk was increased in ABCG2 rs2231142 risk allele carriers in the hypertensive patients compared to non-hypertension patients." (PMID 32183743, 2020). "There was heterogeneity between studies assessing the relationships of ABCG2 rs2231142 polymorphism with sunitinib-induced hypertension, HFS, and neutropenia (I2 = 61.4%, 68.3%, and 68.6%, respectively), and the random-effects model was applied to the analysis." (PMID 33762959, 2021). "According to RGD annotations, there were several genes related to CNS diseases (Abcg2, Ephx2, RGD1563482, Tgfb2, Mal, and Cst3), and 3 genes associated with hypertension (Ephx2, Cst3, and Ltbp2) are found on this list." (PMID 26822062, 2016). "ABCG2 rs2231142 polymorphism can be used as a predictor of SU-induced thrombocytopenia and hand-foot syndrome in Asian people, while ABCB1 rs1128503 polymorphism can be used as a predictor of SU-induced hypertension." (PMID 40755506, 2025). "There was also a negative association between T allele at rs2231142 (ABCG2 gene) and hypertension with aOR (95%CI) 0.86 (0.79–0.93), pcorr 0.0080." (PMID 35633389, 2022). "Since several disease conditions, including hypertension, chronic renal failure, and T2DM are also reported to be associated with high serum uric acid levels, ABCG2 may also play a role in these cases." (PMID 34855903, 2021). "Several other diseases, including hypertension, chronic renal failure, and T2DM have also been reported to be associated with high serum uric acid levels, suggesting that ABCG2 may also play a role in these conditions." (PMID 34855903, 2021). "After adjusting for multiple testing, there was a statistically significant positive association between urate lowering allele at SLC2A9 and hypertension, and negative association between urate raising allele at ABCG2 and hypertension (OR 1.17 and OR 0.86, respectively)." (PMID 35633389, 2022). "However, we could not find associations of ABCG2 rs2231142 polymorphisms with hypertension and neutropenia in the meta-analysis." (PMID 33762959, 2021). "The variability in the serum UA concentrations was best explained by sex; age; BMI; hypertension; hyperglycemia; the serum levels of triacylglycerols, creatinine and GGT; allopurinol intake, MTHFR c.1286A>C, ABCG2 c.421C>A, SLC2A9 c.844G>A and SLC2A9 c.881G>A." (PMID 24827988, 2014). "It reported a statistically significant negative association between SNPs in the ABCG2 and SLC2A9 genes that are associated with high SU and hypertension with evidence of dose response." (PMID 35633389, 2022). "In addition, several statins, used in the therapy of hypercholesterinemia, hypertension, and potentially in T2DM, are also transported substrates of ABCG2, and reduced ABCG2 levels may significantly alter statin absorption and cellular statin levels (see25)." (PMID 33531564, 2021).
neuroblastoma (15 papers, 2008 to 2022). Neuroblastoma (NB) is the most common solid, extracranial childhood tumor. "Nestin and ABCG2 are neural precursor markers and were some of the earliest markers used to describe CSCs in neuroblastoma." (PMID 26729169, 2015). "As predicted, addition of doxorubicin to culture media of neuroblastoma cells increased the percentage of side population cells and correspondingly enriched cultures for ABCG2 expressing cells." (PMID 19156211, 2009). "Both ABCG2 and nestin have since been used as markers for putative CSCs in neuroblastoma." (PMID 26729169, 2015). "Hirschmann-Jax and colleagues were the first to observe that “side population” cancer stem-like cells isolated from cell lines and patients with neuroblastoma expressed high levels of ABCG2 and ABCG3 transporter genes as well as a greater capacity to expel cytotoxic drugs." (PMID 18612434, 2008). "In neuroblastoma cohorts, ChIP analyses revealed that MYC and MYCN can bind at ABCG2 promoter, demonstrating a correlation between level of these transcription factors and ABCG2 mRNA." (PMID 29186899, 2017). "Tumorsphere-derived neuroblastoma cultures were enriched for stemness markers CD133 and ABCG2 in comparison to bulk-grown cells." (PMID 19156211, 2009). "Other studies revealed that neuroblastoma cells express neural precursor markers including CD34, ABCG2, and nestin." (PMID 19156211, 2009). "Four of eight human neuroblastoma cell lines formed tumorspheres in neural stem cell media, and all contained some cells that expressed neurogenic stem cell markers including CD133, ABCG2, and nestin." (PMID 19156211, 2009). "Specifically, high ABCG2 expression clustered with Group 3 tumors, which was engineered by enforced expression of MYC, likely hinting that MYC might be responsible for the high ABCG2 expression as has been previously reported in CML and neuroblastoma." (PMID 29186899, 2017). "Here, neuroblastoma (NB) cell line subtypes were characterized according to embryonic peripheral nervous system development markers (GAP43, Phox2b, Sox10, c-kit, GD2, NF68, vimentin, S100β, calcyclin and ABCG2), morphological features, gene expression and differentiation potential." (PMID 19216736, 2009).
triple-negative breast carcinoma (15 papers, 2014 to 2025). An invasive breast carcinoma which is negative for expression of estrogen receptor (ER), progesterone receptor (PR), and human epidermal growth factor receptor 2 (HER2). "Altogether, our results suggest that the microRNA-449 family might be a potential therapeutic target for the treatment of triple-negative breast cancer since it is implicated in doxorubicin response through ACSL4/ABCG2 axis regulation." (PMID 39174500, 2024). "In conclusion, our findings suggest that CXCL1 secreted by hAdSCs elicits doxorubicin resistance through miR-106a-mediated ABCG2 upregulation in triple negative breast cancer." (PMID 28750689, 2017). "CXCL1 secreted by hAdSCs downregulated miR-106a expression in triple negative breast cancer, and resulted in ABCG2 upregulation and doxorubicin resistance." (PMID 28750689, 2017). "Our findings suggest that CXCL1 secreted by hAdSCs elicits doxorubicin resistance through miR-106a-mediated ABCG2 upregulation in triple negative breast cancer." (PMID 28750689, 2017). "Furthermore, knockdown of Snail using siRNA caused reduced expression of ABCG2 and a diminished number of tumorospheres, thereby indicating that AKT1 is negatively regulating the stemness and cisplatin resistance in triple-negative breast cancers." (PMID 33227065, 2020). "Moreover, MAGL inhibitor JJKK048 was shown to reduce hypoxia-induced resistance to multi-kinase inhibitor regorafenib in triple negative breast cancer cells by downregulating ABCG2 transporter expression, and thus reducing the cellular export of the anticancer drug." (PMID 38004429, 2023). "In addition, its expression in triple-negative breast cancer cells, which are resistant to many chemotherapeutics, increased their sensitivity to doxorubicin and mitoxantrone significantly by directly binding to ABCG2 mRNA and regulating ABCG2 expression." (PMID 26327240, 2015). "In the case of ABCG2, a recent study revealed that RNF180 increases the sensitivity of triple-negative breast cancer cells to gefitinib by degrading RAD51 and downregulation of efflux transporters, including ABCG2, ABCC1, and ABCB1." (PMID 36694209, 2023). "Among them, CXCL1, although it was not the most abundant, increased ABCG2 expression and decreased doxorubicin sensitivity in triple negative breast cancer cells." (PMID 28750689, 2017). "In models of multidrug-resistant, triple-negative breast cancer, jadomycin B has shown promise as it is not a substrate of ABCB1 and ABCG2 drug efflux transporters." (PMID 40253988, 2025). "The present study demonstrated that conditioned medium collected from hAdSC increased ABCG2 protein expression without affecting MRP-1 and P-Gp, and consequently led to decreased intracellular doxorubicin accumulation in MDA-MB-231 triple negative breast cancer cells." (PMID 28750689, 2017).
acute lymphoblastic leukemia (14 papers, 2014 to 2025). Leukemia with an acute onset, characterized by the presence of lymphoblasts in the bone marrow and the peripheral blood. "It has been reported that ABCG2 expression is detected at a higher level in B lineage acute lymphoblastic leukemia than in T lineage acute lymphoblastic leukemia." (PMID 25268163, 2014). "High expression of ABCB1 and ABCG2 has been associated with reduced chemosensitivity and MDR phenotype in blood cancers such as MM, chronic lymphocytic leukemia (CLL), acute lymphocytic leukemia (ALL), and acute myelogenous leukemia (AML), as well as solid tumors such as metastatic breast cancer." (PMID 33807514, 2021). "In this context, it is worth of note that blasts from acute lymphoblastic leukemia with high ABCG2 expression showed a very high resistance to cytarabine despite the fact that cytarabine is not an ABCG2 substrate." (PMID 26536031, 2015). "Until recently, clinical significance of ABCG2 expression has not been established in acute lymphoblastic leukemia." (PMID 25268163, 2014).
diabetes (14 papers, 2011 to 2023). "This correlation of the HbA1c levels with the SNP was not significant in the first-time visitors (untreated) at the diabetes clinic, while the increased HbA1C levels showed a significant correlation with the ABCG2-C421A SNP in the long-time treated patients." (PMID 34855903, 2021). "Abcg2 mRNA and protein expression also increased with the diabetes phenotype, wherein mRNA expression doubled in db/db males and females." (PMID 22524730, 2012). "A study based on the alteration of LSCs in patients with diabetes found that the expression of markers of LSCs such as ΔNp63α, ATP-binding cassette sub-family G member 2 (ABCG2), N-cadherin, K15, K17, K19, and β1 integrin was decreased significantly in the diabetic limbus." (PMID 36589805, 2022).
esophageal cancer (13 papers, 2012 to 2025). A primary or metastatic malignant neoplasm involving the esophagus. "The Eca109/ABCG2 esophageal cancer cells with ABCG2 gene overexpression were resistant to adriamycin (ADM), daunorubicin (DNR) and mitoxantrone (MIT), which indicated that ABCG2 may be associated with drug resistance in esophageal cancer." (PMID 24179544, 2013). "In addition, the drug tolerance of esophageal carcinoma and the metastasis of this tumor may be associated with the expression of ABCG2/V-ATPase." (PMID 23244569, 2012). "Other studies confirmed ABCG2 protein overexpression in the majority (75%) of esophageal cancer tissues and high ABCG2 protein correlates with poor prognosis of ESCC patients." (PMID 33390934, 2020). "Available studies suggest that expression of several ABC proteins (ABCB1, ABCC2, and ABCG2) correlates with prognosis or response to therapy in esophageal cancer patients." (PMID 33390934, 2020). "Another cell surface marker potentially identifying esophageal cancer stem cells is ABCG2, a member of group G in the ATP-binding cassette (ABC) transporter family." (PMID 28930282, 2017). "Several genes/pathways have been implicated to esophageal cancer migration, such as Cdc42, HGF/SF, Androgen receptor, RhoA, Rac-1, and Cdc42, VEGF, HER2, PLCE1, ABCG2/V-ATPase, MMS19." (PMID 28147311, 2017). "Mithramycin is also reported to repress basal and cigarette smoke-induced expression of ABCG2 and inhibits stem cell signaling in lung and esophageal cancer cells." (PMID 26484141, 2015). "In order to investigate the correlation between drug resistance in esophageal cancer and ABCG2 expression, the ABCG2 gene was transfected into the Eca109 esophageal cancer cell line to establish Eca109/ABCG2 cells." (PMID 24179544, 2013). "The esophageal cancer drug resistant Eca109/ABCG2 cell line was established by transfecting the ABCG2 gene into Eca109 cells." (PMID 24179544, 2013). "In the present study, the gene and protein expression of ABCG2 was detected by various experimental methods, to study the correlation between ABCG2 expression and the resistance of esophageal carcinoma." (PMID 24179544, 2013). "The correlation between ABCG2 expression in esophageal carcinoma and MDR, and the reversal of MDR by Art were investigated in the present study." (PMID 24179544, 2013). "Similarly, previous studies showed that ART reversed the ADR resistance by reducing ABCG2 expression in esophageal cancer in vitro and in vivo." (PMID 35547242, 2019). "ABCG2 expression is upregulated by cigarette smoking and is inhibited by the drug mithramycin: remarkably, this drug decreases the proliferation and the tumorigenicity of esophageal cancer cells." (PMID 28930282, 2017). "In summary, ABCG2 expression participated in the MDR of esophageal cancer." (PMID 24179544, 2013). "The present study discussed the association between ABCG2 expression and MDR in esophageal cancer." (PMID 24179544, 2013). "There are few reports detailing ABCG2 expression in esophageal cancer." (PMID 23244569, 2012). "It was discovered that by favorably activating the ATP-binding cassette sub-family G member 2 (ABCG2) protein, HOTTIP controls medication resistance in esophageal cancer." (PMID 40616679, 2025). "The present study investigated a potential correlation between ABCG2 expression and MDR in esophageal cancer." (PMID 24179544, 2013). "In cancers like esophageal cancer, targeting HOTTIP-mediated pathways (e.g., ABCG2) could enhance chemotherapeutic efficacy." (PMID 40616679, 2025). "The present study aimed to investigate the correlation between ABCG2 expression and the MDR of esophageal cancer and to estimate the therapeutic benefit of downregulating ABCG2 expression and reversing chemoresistance in esophageal cells using artesunate (Art)." (PMID 24179544, 2013).
lymph node metastasis (13 papers, 2011 to 2023). "In one of these studies, high ABCG2 immunoreactivity was reported to correlate with the presence of lymph node metastases and in the other study high ABCG2 immunoreactivity was associated with shorter OS." (PMID 32708825, 2020). "The authors have found that strong membranous ABCG2 expression is significantly associated with higher Dukes’ stage, lymph node metastasis, and distant metastasis and that it is an independent prognostic factor of overall survival." (PMID 27257141, 2016). "The overexpression of ABCG2 was reported to be correlated with lymph node metastasis in ESCC patients." (PMID 30979011, 2019). "One study found that high expression of stem cell markers including ABCG2 correlated with poor patient prognosis, and another study found high expression of ABCG2 to be correlated to the presence of lymph node metastases." (PMID 28880238, 2017). "ABCG2 correlated with Her-2 expression, lymph node metastasis and clinical stage in breast invasive ductal carcinoma." (PMID 21943250, 2011). "Besides, the expression of ABCG2 is correlated with lymph node metastasis (p = 0.049) and clinical stage (p = 0.015), which suggests that the patients with high expression of ABCG2 may have a worse prognosis than those with low expression of ABCG2." (PMID 21943250, 2011). "A statistically significant correlation was demonstrated between ABCG2 expression and HER-2 expression (p = 0.001), lymph node metastasis (p = 0.049), and clinical stage (p = 0.015) respectively." (PMID 21943250, 2011). "The increased TOX3, WDR5, and ABCG2 expression was respectively detected in the majority of metastatic CRCs as compared with those with no lymph node metastasis." (PMID 37708089, 2023). "ABCG2 is a family member of the ABC transporter, and its positive expression in laryngeal carcinoma has been related to tumor differentiation, age, sex, and presence of loco-regional lymph node metastasis." (PMID 35681602, 2022). "Furthermore, a high protein expression of ABCG2 was found in 30% of cases with lymph node metastases compared to 6.7% in cases without positive lymph nodes (p < 0.025)." (PMID 28880238, 2017). "To clarify the clinical significance of TOX3-WDR5/ABCG2 signaling axis in CRC progression, we divided the 94 patients into 2 groups based on the CRC tissue microarray, with or without lymph node metastasis for clinical analysis." (PMID 37708089, 2023).
retinoblastoma (13 papers, 2007 to 2025). A malignant tumor that originates in the nuclear layer of the retina. "For example, curcumin inhibits the expression of ABCC1/MRP1 in retinoblastoma cells and suppresses the activity of ABCG2/BCRP in mice." (PMID 26305906, 2015). "Small populations of retinoblastoma cells have been found to express stem cell–associated markers SOX2, aldehyde dehydrogenase 1, p63, and ABCG2, and to exclude Hoechst dye." (PMID 23559850, 2013). "High expression of ABCG2 has been detected in CSCs isolated from embryonic cancer, retinoblastoma, lung, liver, pancreas and gallbladder cancer." (PMID 22209971, 2012). "Expression of ABCG2 and MCM2 has been associated with increased tumor invasiveness in retinoblastoma." (PMID 17615543, 2007). "A therapy that decreases the bulk of the retinoblastoma tumor using Wnt activator proteins would need to be used in combination with inhibitors of the Wnt pathway that are specifically targeted to the stem cell population, potentially by using ABCG2 or other cancer stem cell marker genes." (PMID 20069066, 2010). "Therefore, the extent of CD133 expression, in addition to expression of the ABCG2 drug transporter, may be another factor to consider with regard to chemotherapy resistance in retinoblastoma." (PMID 17615543, 2007). "Our results showed that single exposure to chemotherapy or even longer and continuous treatments with melphalan or topotecan at the IC50 did not alter ABCB1, ABCC1, or ABCG2 expression levels in retinoblastoma and HUVEC cells." (PMID 27467588, 2016). "The heterogeneity of these cell lines is not surprising, considering that in our previous studies, ABCG2 was expressed in 4% of retinoblastoma cell lines." (PMID 26317026, 2013).
small cell lung carcinoma (13 papers, 2014 to 2025). Small cell lung cancer (SCLC) is a highly aggressive malignant neoplasm, accounting for 10-15% of lung cancer cases, characterized byrapid growth, and early metastasis. "One study has found that ABCB1 and ABCG2 might mediate chemoresistance in HER2-positive small cell lung cancer cells." (PMID 34244494, 2021). "Among the small cell lung cancer cell lines, in GLC-4 cells the promoters of both ABCB1 and ABCG2 were found to be higher methylated than in DMS114 cells." (PMID 27689338, 2016). "Inhibition of PFKFB3 by the glycolytic inhibitor PFK158 and by shRNA stable knockdown in small cell lung carcinoma (SCLC) cell lines inhibited glycolysis, proliferation, spheroid formation, and the expression of cancer stem cell markers CD133, Aldh1, CD44, Sox2, and ABCG2." (PMID 35804016, 2022).
breast adenocarcinoma (12 papers, 2015 to 2024). "On the other hand, ABCG2 over-expressing breast adenocarcinoma cells were hypersensitive to the chalcone as compared to their parental cells." (PMID 34361789, 2021).